SLC75A1 (solute carrier family 75 member 1)
Description:
Probable organic anion transporter which may serve as a transporter for some non-steroidal anti-inflammatory drugs (NSAIDs) as well as other organic anions across the luminal membranes of renal proximal tubules at the final excretion step into the urine.
Synonyms: MFSD10; TETRAN; IT10C3; TETTRAN
Tractability: Small molecule: a structure with a bound ligand is known. Antibody: UniProt places it where antibodies can reach, with high confidence; UniProt predicts a signal peptide or a membrane-spanning region; its Gene Ontology location is reachable by antibodies, with medium confidence. PROTAC: ubiquitination databases record sites on it; its protein half-life has been measured.
Gene: Protein-coding gene on chromosome 4 (2,930,559 to 2,935,462, reverse strand). Ensembl gene ENSG00000109736.
Subcellular location: Nucleus inner membrane; Cell membrane
Subcellular location (Human Protein Atlas): Nuclear membrane; Nucleoplasm
Gene Ontology:
Molecular function: protein binding; transmembrane transporter activity; tetracycline transmembrane transporter activity
Biological process: sodium-independent organic anion transport; tetracycline transmembrane transport; transmembrane transport
Cellular component: cytoplasmic vesicle membrane; brush border membrane; membrane; nuclear inner membrane; plasma membrane
Genetic constraint (gnomAD): Loss-of-function variants: 56 observed, 43.67 expected, observed/expected ratio (o/e) 1.28, 90% interval 1.03 to 1.6. The synonymous counts are far from expectation, so gnomAD's model fits this gene poorly and the ratio says little. Missense variants: 756 observed, 585.97 expected, observed/expected ratio (o/e) 1.29, 90% interval 1.22 to 1.37. Synonymous variants: 361 observed, 269.36 expected, observed/expected ratio (o/e) 1.34, 90% interval 1.23 to 1.46.
Homologues: Orthologues: macaque MFSD10 (97% identical), chimpanzee MFSD10 (87% identical), pig MFSD10 (86% identical), mouse Mfsd10 (80% identical), rat Mfsd10 (77% identical), dog MFSD10 (75% identical), tropical clawed frog mfsd10 (61% identical), zebrafish mfsd10 (57% identical), Drosophila melanogaster rtet (41% identical), Caenorhabditis elegans mfsd-10 (38% identical), tropical clawed frog mfsd14b (22% identical), zebrafish mfsd14a2 (22% identical), and 18 more. Paralogues in human: SLC67A2 (21% identical), SLC71A1 (21% identical), SLC71A2 (21% identical), MFSD8 (16% identical), SLC61A1 (16% identical), MFSD1 (14% identical).
Diseases named in the same sentence as SLC75A1 in open-access papers:
SLC75A1 is named in the same sentence as 1 disease in open-access papers, as found by Europe PMC text mining. Sharing a sentence is not in itself a finding about the gene and the disease.
SLC75A1 shares sentences with these, for which no sentence is quoted: Wolf-Hirschhorn syndrome (1 paper).